GLS2 (glutaminase 2)
Diseases named in the same sentence as GLS2 in open-access papers (continued):
Sharing a sentence is not in itself a finding about the gene and the disease.
colon carcinoma (9 papers, 2013 to 2025). "Thus, GLS2 expression proved to be diminished in colon tumor tissues compared to adjacent non-tumor tissues and, as in the case of HCC, promoter methylation was found to be a key mechanism underlying GLS2 silencing in colon cancer." (PMID 38067269, 2023). "Overexpression of GLS2 in human lung, liver, and colon cancer cells has been proved to induce significant inhibitions in tumor growth and proliferation." (PMID 35368652, 2022). "Our data thus provide useful insights into the possible role of Gls2 as a functional tumor suppressor involved in human liver and colon cancers." (PMID 24330717, 2013). "We provide evidence showing that epigenetic silencing of Gls2 via promoter hypermethylation is common in human liver and colon cancers and Gls2 appears to be a functional tumor suppressor involved in the liver and colon tumorigenesis." (PMID 24330717, 2013). "Similar trend was also observed in colon cancer tissues when we compared the Gls2 mRNA level among 5 pairs of colon tumor tissues vs the adjacent non-tumor tissues." (PMID 24330717, 2013). "Here, we investigated Gls2 expression and its promoter methylation status in human liver and colon cancers." (PMID 24330717, 2013). "In this part of our study, we first examined Gls2 mRNA level in an array of human liver and colon cancer cell lines." (PMID 24330717, 2013). "Our results revealed that Gls2 was downregulated in human liver and colon cancer cell lines as well as in human liver tumor tissues, and the lower level of Gls2 was correlated with its promoter hypermethylation." (PMID 24330717, 2013). "mRNA expression of Gls2 was determined in human liver and colon cancer cell lines and HCC tissues by real-time PCR and promoter methylation was analyzed by methylation-specific PCR (MSP) and validated by bisulfite genome sequencing (BGS)." (PMID 24330717, 2013). "Although promoter methylation is an important mechanism in silencing Gls2 in human liver and colon cancer cells, we cannot exclude the involvement of other mechanisms responsible for Gls2 downregulation, such as histone acetylation." (PMID 24330717, 2013). "In summary, we found that Gls2 is frequently downregulated in human liver and colon cancer cells and also in primary HCC tissues, and such downregulation is correlated to its promoter hypermethylation." (PMID 24330717, 2013). "In reference to colon cancer, in which GLS2 expression is high, GLS2 inhibitors were discovered, which could be used as a potential anti-cancer target." (PMID 30871151, 2019). "GLS2 expression was reported to be significantly increased in 186 human colon carcinoma samples." (PMID 25026281, 2014). "In order to know whether Gls2 expression is correlated to DNA methylation, both liver and colon cancer cells were treated with a demethylation reagent Aza." (PMID 24330717, 2013). "Gls2 promoter methylation was readily detected in human liver and colon cancer cells but not in the normal tissues." (PMID 24330717, 2013). "Even though the analysis was performed on a small number (n = 5) of tissues, and the level of GLS2 protein was not examined, the results of studies on human colon cancer cells (HCT116) revealed that an ectopic expression of GLS2 markedly reduced the viability and number of cell colonies." (PMID 38067269, 2023). "First, we observed reduced Gls2 mRNA level in a selected group of liver and colon cancer cell lines and in the cancerous tissues from 20 HCC and 5 human colon cancer patients in comparison to their non-cancerous counter parts." (PMID 24330717, 2013).
gastric cancer (8 papers, 2019 to 2024). A primary or metastatic malignant neoplasm involving the stomach. "GLS mutations mainly occurred in uterine, lung, and stomach cancer, whereas GLS2 mutations were mainly found in uterine, lung, and stomach cancer." (PMID 30871151, 2019). "GLS2 overexpression suppressed the viability of gastric cancer MGC-803 cells and their ability to migrate; it also induced apoptosis." (PMID 38067269, 2023). "Inhibiting ALKBH5 upregulates the m6A levels of glutaminase 2 (GLS2) and inhibits the malignant biological behavior of gastric cancer cells." (PMID 37325047, 2023). "Upregulation of GLS2 exhibited antitumor effects in gastric cancer by promoting ferroptosis." (PMID 34277151, 2021). "More recently, the downregulation of GLS2 expression was noted in a cohort of 36 gastric cancer tissues compared to the adjacent non-cancer tissues." (PMID 38067269, 2023).
neuroblastoma (8 papers, 2012 to 2024). Neuroblastoma (NB) is the most common solid, extracranial childhood tumor. "Human neuroblastoma SHSY-5Y cells express both GLS2 transcript variants (as checked by qPCR analysis, results not shown) and were used as a control for antibody validation in mammalian tissues." (PMID 22679499, 2012). "We then sought to determine whether elevated GLS2 expression is functionally linked to N-Myc mediated neuroblastoma cell proliferation." (PMID 26528759, 2015). "In this study, our RNA-seq barely detected the expression of GLS2 in the neuroblastoma cell models we used, indicating that GLS is the major enzyme that catalyzes glutamine in these model systems." (PMID 38488852, 2024). "High GLS2 expression was significantly correlated with poor survival, while GLS expression was negatively associated with the prognosis of neuroblastoma patients." (PMID 38067269, 2023). "Of note, GLS2 is substantially upregulated in human neuroblastoma tumors harboring MYCN amplification, and correlates with increased malignancy in a mouse transgenic neuroblastoma model." (PMID 26528759, 2015). "Unexpectedly, we showed in the current study that MYCN-amplified neuroblastoma cells predominantly rely on activation of GLS2-mediated glutamine deamidation to sustain TCA cycle anapleurosis and biosynthetic activities." (PMID 26528759, 2015). "Nevertheless, results shown here depicted a new layer of regulation in control of tumor glutamine metabolism and provided a molecular explanation for the functional significance of GLS2 overexpression observed in MYCN-amplified neuroblastomas." (PMID 26528759, 2015). "Altogether, these data suggest that N-Myc promotes oxidative glutamine metabolism predominantly through selective GLS2 induction in MYCN-amplified neuroblastoma cells." (PMID 26528759, 2015). "Nevertheless, these data demonstrated that GLS2-mediated glutamine catabolism coordinates both of the energy-generating pathways, oxidative phosphorylation and aerobic glycolysis, to stimulate neuroblastoma cell growth and proliferation." (PMID 26528759, 2015). "Taken together, these results support that N-Myc selectively activates GLS2 expression to promote glutamine catabolism in MYCN-amplified neuroblastoma cells." (PMID 26528759, 2015). "Surprisingly, while elevated GLS2 expression is significantly correlated with a poor neuroblastoma patient survival, GLS1 expression was paradoxically associated with favorable prognosis in these patient populations." (PMID 26528759, 2015). "We reasoned that if GLS2-mediated glutamine deamidation is critical to the survival of MYCN-amplified neuroblastoma cells, then, depletion of GLS2 expression should achieve a phenotype similar to that caused by glutamine starvation." (PMID 26528759, 2015). "Analysis of microarray data obtained from mouse neuroblastoma tumors bearing the human MYCN transgene further corroborated that GLS2 expression was significantly elevated during aggressive tumor progression." (PMID 26528759, 2015). "We reasoned if GLS2 activity is indeed essential for glutamine-dependent anapleurosis in MYCN-amplified neuroblastoma cells, then, GLS2 suppression should recapitulate glutamine deprivation in regulation of glucose metabolism." (PMID 26528759, 2015). "Xiao and colleagues reported a pro-oncogenic function of GLS2 in neuroblastoma." (PMID 38067269, 2023). "However, in neuroblastoma, GLS2 is a critical downstream target of N-myc, suggesting that the role of GLS2 in cancer is context dependent." (PMID 28811348, 2017).
neuroblastoma (continued). "Taken together, these results demonstrate an important role of GLS2 in oxidative glutamine metabolism driven by oncogenic N-Myc, suggesting targeting GLS2 may represent an effective treatment approach to neuroblastoma patients exhibiting MYCN-amplification." (PMID 26528759, 2015). "Notably, abrogation of N-Myc function also significantly inhibited glutamine consumption and glutamate production, arguing that N-Myc promotes glutamine deamidation in MYCN-amplified neuroblastoma cells in part through GLS2 activation." (PMID 26528759, 2015). "Further analysis showed that inhibition of GLS2 expression also profoundly inhibited ATP generation, validating our previous findings that glutamine metabolism provides an important energy source (ATP) to support neuroblastoma cell growth." (PMID 26528759, 2015). "We then established subcutaneous xenografts using Kelly cells to confirm whether GLS2-mediated glutamine catabolism could affect the tumorigenic capacity of MYCN-amplified neuroblastoma cells in vivo." (PMID 26528759, 2015). "Indeed, elevated GLS2 expression is significantly correlated with a poor neuroblastoma patient survival." (PMID 26528759, 2015). "It is worth noting that western blot analysis of human neuroblastoma SHSY-5Y cell lysates revealed two protein bands with molecular masses compatible with GAB and LGA, confirming the existence of two GLS2 products." (PMID 38067269, 2023). "We demonstrated that GLS2 can be targeted to the cell nucleus in human GBM, neuroblastoma and HCC cells." (PMID 32042057, 2020). "Our results reveal that metabolic control of N-Myc induced neuroblastomas differs from that of c-Myc transformed Burkitt's lymphomas, with one of the checkpoints being differential regulation of GLS1 versus GLS2 activation." (PMID 26528759, 2015). "Indeed, further analyses have revealed that GLS2 silencing substantially reduced proliferation and clonogenic potential in two MYCN-amplified neuroblastoma cell lines, Kelly and BE-2C, and attenuated their ability to form tumors in vivo." (PMID 38067269, 2023). "We analyzed GLS2 expression in HCC, GBM and neuroblastoma cells, as well as in monkey COS-7 cells." (PMID 32042057, 2020). "We report here that N-Myc, an essential Myc family member, promotes conversion of glutamine to glutamate in MYCN-amplified neuroblastoma cells by directly activating GLS2, but not GLS1, transcription." (PMID 26528759, 2015). "Although exogenous c-Myc similarly activates this reporter in 293T cells, it is unlikely to contribute to GLS2 activation in MYCN-amplified neuroblastoma cells as these cells barely exhibit detec-Myc expression." (PMID 26528759, 2015). "Whether TXNIP virtually functions downstream of GLS2 to restrict aerobic glycolysis needs further investigation, though we observed prominent induction of this protein in MYCN-amplified neuroblastoma cells upon glutamine starvation and GLS2 knockdown." (PMID 26528759, 2015). "Moreover, elevated GLS2 expression is significantly elevated in MYCN-amplified neuroblastomas in comparison with non-amplified ones, correlating with unfavorable patient survival." (PMID 26528759, 2015). "Conceivably, a consequence of this N-Myc dependent GLS2 activation is the reprogramming of mitochondrial metabolism to depend on glutamine catabolism to sustain cellular viability and TCA cycle anapleurosis, triggering neuroblastoma cellular addiction to glutamine as a bioenergetic substrate." (PMID 26528759, 2015). "Interestingly, GLS2 knockdown significantly decreased both GSH content and GSH/GSSG ratio, suggesting that enhanced glutamine deamidation by GLS2 plays an important role in proper redox homeostasis maintenance in MYCN-amplified neuroblastoma cells." (PMID 26528759, 2015). "Thus, N-Myc-dependent GLS2 activation may result in the reprogramming of cellular metabolism to maintain the viability and anaplerosis of the TCA cycle, ultimately leading to the Gln dependence of neuroblastoma cells." (PMID 38067269, 2023).
neuroblastoma (continued). "Importantly, we uncovered a previously unknown mechanism involved in regulation of GLS2 expression in MYCN-amplified neuroblastoma cells, and identified N-Myc as a novel activator selectively upregulating GLS2 (but not GLS1) expression." (PMID 26528759, 2015). "N-MYC, an important member of the MYC family, can directly accelerate the activation of GLS2 rather than GLS1 and promote oxidative glutamine metabolism in MYCN-amplified neuroblastoma cells." (PMID 37249801, 2023). "The induction of MYCN expression in SHEP MYCN-ER neuroblastoma cells, which carry a single copy of the MYCN gene, led to a time-dependent activation of GLS2 but not GLS." (PMID 38067269, 2023).
lung carcinoma (7 papers, 2014 to 2024). "The 8 FRGs (ACSL3, FADS2, GLS2, HSF1, PANX1, PHKG2, VDAC2, and CDKN1A) that we selected to be associated with the diagnosis and prognosis of lung cancer have been shown to play important roles in cancer and tumor immunity." (PMID 38743344, 2024). "In contrast, whereas GLS demonstrated anti-oncogenic roles in bladder, kidney, and lung cancer, GLS2 acted as a tumor suppressor in brain, kidney, pancreatic, and skin cancer." (PMID 30871151, 2019). "Although the survival analysis uncovered both high and low expression levels of GLS2 in certain types of cancer, including bladder and lung cancer, the Oncomine databased was unable to provide such expression patterns, unlike for GLS." (PMID 30871151, 2019). "In contrast, GLS2 was upregulated in bladder, colon, rectum, head-and-neck, peritoneum, and lung cancer, but downregulated in brain, liver, and pancreatic cancer." (PMID 30871151, 2019). "GLS and GLS2 inhibitors were discovered which were able to inhibit cell proliferation in various types of cancer, including breast, blood, and lung cancer." (PMID 30871151, 2019). "GLS2 depletion in HT1299 lung cancer cells by siRNA increased the apoptosis cell population and, in combination with the inducers of ROS-dependent apoptosis doxorubicin or n-butyrate, further augmented the percentage of apoptotic cells." (PMID 25026281, 2014). "Notably, glutaminase 2 (GLS2) is overexpressed in lung carcinoma and colorectal cancer." (PMID 35903696, 2022). "The analysis of data from the Oncomine database has revealed the overexpression of GLS2 compared to non-tumorigenic tissues in bladder, colon, rectum, head-and-neck, peritoneum, and lung cancers." (PMID 38067269, 2023).
colorectal cancer (4 papers, 2019 to 2025). A primary or metastatic malignant neoplasm that affects the colon or rectum. "Interestingly, the expression of GLS2 was replaced by GLS1 gradually during colorectal cancer development in tissue microarrays." (PMID 30674873, 2019).
hyperglycaemia (4 papers, 2019 to 2024). "Our results were partly supported by findings from a previous study, where the authors found that reducing glutamine metabolism (loss-of-function of GLS2) in the liver resulted in decreased severity of hyperglycaemia (increased plasma levels of glutamine and reduced levels of fasting glucose)." (PMID 38017422, 2023). "Despite significant hyperglycaemia in Gls2 CKO mice after glucose loading, plasma glucagon, which is generated from pancreatic α-cells and functions as a key regulator of hepatic gluconeogenesis, was increased." (PMID 37147373, 2023). "GLS2, the glutaminolysis key regulator in pancreatic β-cells, maintains glucose homeostasis under the condition of hyperglycaemia." (PMID 37147373, 2023). "Although the exact mechanism by which β-cell-specific GLS2 regulates insulin and glucagon requires further study, our data indicate that GLS2 in pancreatic β-cells maintains glucose homeostasis under the condition of hyperglycaemia." (PMID 37147373, 2023). "Despite marked hyperglycaemia, impaired insulin secretion and paradoxical glucagon elevation were observed in high-fat diet-fed Gls2 CKO mice." (PMID 37147373, 2023). "Intriguingly, blocking Glu production by targeting hepatic GLS2 activity ameliorates hyperglycemia in both humans and mice, suggesting a possible new therapeutic avenue to treat hyperglycemia." (PMID 31487814, 2019). "Contrary to the phenomenon that hepatic gluconeogenesis generally decreases during hyperglycaemia, Gls2 CKO mice revealed a significant increase in blood glucose levels from 60 min after pyruvate administration compared to the levels in RIP-Cre mice, indicating an increase in gluconeogenesis." (PMID 37147373, 2023). "Furthermore, we found that impairment of Gls2 expression in pancreatic β-cells during hyperglycaemia resulted in the development of significant diabetes mellitus via impairment of insulin increase along with a paradoxical increase in glucagon despite the high plasma glucose." (PMID 37147373, 2023).
leukemia (4 papers, 2019 to 2025). A malignant (clonal) hematologic disorder, involving hematopoietic stem cells and characterized by the presence of primitive or atypical myeloid or lymphoid cells in the bone marrow and the blood. "We first postulated a completely different role for GLS and GLS2 isoforms in cancer based on their relative expression patterns in human leukemia, breast cancer cells, and hepatocellular transformation." (PMID 32042057, 2020).
pancreatic cancer (4 papers, 2019 to 2023). "The activation of GLS1 was found to be critical for colon cancer growth, whereas hypoxia-activated GLS2 was found in pancreatic cancer." (PMID 35158820, 2022). "However, GLS2 expression was shown to strongly depend on the microenvironment as enhanced GLS2 expression was reported under hypoxia in pancreatic cancer." (PMID 35158820, 2022). "Based on the protein expression profiles of pancreatic cancer samples collected in the Human Protein Atlas (HPA) database, LDHA, GLS2, and SLC38A10 exhibited higher expression levels in pancreatic cancer." (PMID 37333498, 2023).
brain tumors (3 papers, 2014 to 2020). "GLS2 displays a tumor suppressive function in liver and brain tumors, where GLS2 expression is frequently decreased." (PMID 33182266, 2020). "Interestingly, it was reported that the expression of GLS2 is also reduced in brain tumors." (PMID 24797434, 2014).
breast tumors (3 papers, 2011 to 2021). "Although GLS2 tends to exhibit tumor-suppressing activity, it was reported as a pro-tumorigenic gene in luminal-subtype breast tumors." (PMID 34573287, 2021). "This concordance indicates the differential expression of GLUL, GLS and GLS2 in the luminal and basal-type cancer cell lines reflects similar systematic differences in primary breast tumors." (PMID 21852960, 2011). "In a breast tumor expression dataset, we found significantly different expression levels of GLUL, GLS and GLS2 in the corresponding luminal (luminal A and B) and basal-types of breast tumors." (PMID 21852960, 2011).
colorectal adenocarcinoma (3 papers, 2019 to 2025). The most common type of colorectal carcinoma. "Conversely, the intensity of GLS2 expression was relatively high in normal colorectal (53.3%) and inflammatory hyperplasia tissues (64.7%), and was low in colorectal adenocarcinoma (p < 0.0001)." (PMID 30674873, 2019).